CLPP (caseinolytic mitochondrial matrix peptidase proteolytic subunit)
Diseases named in the same sentence as CLPP in open-access papers (continued):
Sharing a sentence is not in itself a finding about the gene and the disease.
hepatic disorders (2 papers, 2025). "In conclusion, ClpP acts as both a guardian and a potential driver in liver disease progression." (PMID 41155556, 2025). "LON-CLPP protease complex: Perturbations in mitochondrial function and the accumulation of damaged proteins are central to the development and progression of liver diseases, making the role of mitochondrial proteases, such as LON and CLPP, crucial for maintaining cellular homeostasis." (PMID 40806358, 2025).
liver cancer (2 papers, 2024 to 2025). An epithelial or non-epithelial malignant neoplasm that arises from the liver. "For example, TG42 and TG53, modified analogs of the first ClpP inhibitor trans-β-lactones, inhibit ClpP proteolytic activity, reduce cell migration and induce apoptosis in liver cancer cells." (PMID 39261452, 2024).
lung squamous cell carcinoma (2 papers, 2023 to 2025). "Here, the authors develop a potent activator ZK53 that is highly selective on human ClpP but inactive toward bacterial ClpP proteins, and show that ZK53 causes cell cycle arrest via ClpP on lung squamous cell carcinoma cells and exhibits therapeutic effects in animal models." (PMID 37923710, 2023). "However, we are currently unaware of any studies using selective and potent ClpP activators in lung squamous cell carcinoma." (PMID 37923710, 2023).
male infertility (2 papers, 2022). The inability of the male to effect fertilization of an ovum after a specified period of unprotected intercourse. "Whereas, CLPP knockout mice exhibit reduced prenatal/postnatal survival, growth retardation, movement impairment, mild respiratory defects, and female and male infertility." (PMID 35310970, 2022).
nosocomial infection (2 papers, 2022 to 2024). An infection acquired in a hospital or other healthcare setting. "Aberrant activation of bacterial ClpP protease is a promising method of treating nosocomial infections with antibiotic-resistant Gram-positive bacteria." (PMID 36376309, 2022).
osteosarcoma (2 papers, 2021 to 2023). A usually aggressive malignant bone-forming mesenchymal neoplasm, predominantly affecting adolescents and young adults. "Moreover, knockdown of ClpP in mtDNA depleted osteosarcoma cells (143B Rho 0), cells not depending on OXPHOS, had little effect on cell viability compared to osteosarcoma 143B cell with normal mtDNA content." (PMID 34207660, 2021).
Ovarian Tumors (2 papers, 2022 to 2025). "The significant finding of this study was that ONC201 reduced the expression of DRD2, and inhibited ovarian tumor growth and reduced the ability of invasion via activation of ClpP induced oxidative stress pathways and inactivation of P13K/AKT/mTOR and MAPK pathways." (PMID 35372029, 2022).
pancreatic cancer (2 papers, 2023 to 2025). "In human pancreatic cancer BxPC-3 tumor cell lines, by creating a doxycycline-induced ClpP expression system, compared with the wild-type cells, the doxycycline-induced group had inhibited tumor cell growth and proliferation." (PMID 40395852, 2025). "Wang’s team development a small molecule agonist ZG111 of the mitochondrial caseinolytic protease P (ClpP) that produces tumor inhibitory effects in pancreatic cancer cell lines and mouse models." (PMID 36834681, 2023).
pneumococcal infection (2 papers, 2021). Infections with bacteria of the species streptococcus pneumoniae. "ClpP is required for nasopharyngeal colonization, lung infection, and systemic disease in several mouse models of pneumococcal infection using ClpP-negative strains and their parental counterparts." (PMID 33660565, 2021).
prostate adenocarcinoma (2 papers, 2016 to 2021). "Similarly, ClpP was highly expressed in primary tissue samples of human prostatic adenocarcinoma, but not normal prostate epithelium." (PMID 27389535, 2016).
prostate tumor (2 papers, 2022 to 2025). "The co-expression of ClpP and LONP1 in prostate tumors, both located on chromosome 19q13, suggests a coordinated oncogenic stress–adaptive axis." (PMID 41155556, 2025). "Immunohistochemical (IHC) analysis of HSP60 and ClpP in a TMA containing 128 human PCa and MN tissues revealed significantly higher expression of both proteins in prostate tumors." (PMID 35653190, 2022). "Having shown that (a) HSP60 chaperonin and ClpP physically interact, and (b) HSP60 is required for prostate tumor development, we aimed to decipher the importance of the HSP60-ClpP interaction in maintaining mitochondrial health and PCa cell survival." (PMID 35653190, 2022).
synucleinopathies (2 papers, 2019 to 2025). "Our findings provide novel insights into the mechanism underlying αSyn-induced neuronal pathology, and they suggest that ClpP might be a useful therapeutic target for PD and other synucleinopathies." (PMID 30877431, 2019). "Thus, our findings should stimulate the development of ClpP modulators as potential disease-modifying therapeutic agents in PD and other synucleinopathies." (PMID 30877431, 2019).
tuberculosis (2 papers, 2023 to 2024). A chronic, recurrent infection caused by the bacterium Mycobacterium tuberculosis. "Here, we present our method, TamGen, which not only achieved state-of-the-art performance in benchmark testing but also discovered several compounds with high inhibitory activities against the ClpP protease of Mycobacterium tuberculosis, the causative pathogen of tuberculosis." (PMID 39472567, 2024). "The success of generating ClpP inhibitory compounds underscores the immense promise of TamGen in designing novel drug candidates and addressing drug-resistant Tuberculosis, implying its broad applications in drug design to treat other diseases." (PMID 39472567, 2024).
auditory neuropathy (1 paper, 2021). A hearing disorder characterized by impaired transmission of signals through the auditory nerve, resulting in mild to severe hearing loss and poor speech perception. "In the present paper we describe a child affected by PRLTS3, due to CLPP homozygous mutations, presenting auditory neuropathy spectrum disorder (ANSD) with bilateral progressive SNHL." (PMID 34842607, 2021).
bladder tumor (1 paper, 2021). "Samples of the main bladder tumor and healthy-looking bladder wall from patients classified as NMIBC were tested for Mfn2 and ClpP." (PMID 34441434, 2021).
brain cancer (1 paper, 2025). A primary or metastatic malignant neoplasm affecting the brain. "Only a limited number of research groups are investigating ClpP in the context of brain cancers, even though these malignancies often exhibit a strong dependence on mitochondrial metabolism." (PMID 41155556, 2025).
brucellosis (1 paper, 2023). Brucellosis is a bacterial infection that spreads from animals to people via unpasteurized dairy products or by exposure to contaminated animal products or infected animals. "In this study, the ClpP protein is also closely involved in virulence in Brucella, which indicates that this protease has potential applications in the development of therapeutic drugs for brucellosis." (PMID 37612737, 2023).
colon cancer (1 paper, 2018). "Our results suggested that CLPP/VSVMP mRNA complex was more capable than equal amount of plasmid complex in treating C26 colon cancer in vitro, with an inhibition rate of 70.6% versus 59.6% (P < 0.05)." (PMID 35539419, 2018). "Overall, our data suggested that CLPP/VSVMP mRNA complex are capable of treating C26 colon cancer by inducing apoptosis and angiogenesis inhibition without high safety." (PMID 35539419, 2018).
foreign body (1 paper, 2017). Extraneous material within the body. "A murine model of subcutaneous foreign body infection was used to investigate the impact of clpP on biofilm-associated infection in vivo." (PMID 28555174, 2017).
gastric adenocarcinoma (1 paper, 2025). "ClpP dysregulation in gastric adenocarcinoma underscores a broader landscape of mitochondrial dysfunction and highlights hClpP as a compelling therapeutic target." (PMID 41155556, 2025).
gastric cancer (1 paper, 2025). A primary or metastatic malignant neoplasm involving the stomach. "Gastric carcinoma shows differential ClpP expression associated with mitochondrial stress and carcinogenesis." (PMID 41155556, 2025). "Although performed in immunodeficient mice and limited to a defined panel of models, these results confirm functional involvement of ClpP in ISR-driven apoptosis in gastric cancer." (PMID 41155556, 2025). "Proteomic profiling of human gastric carcinoma has revealed altered expression of mitochondrial ClpP, indicating its potential contribution to gastric tumorigenesis." (PMID 41155556, 2025). "Pharmacological activation of ClpP by ONC201 restores apoptotic signaling through ISR engagement and TRAIL receptor sensitization, providing a tumor-selective and well-tolerated strategy for gastric cancer treatment." (PMID 41155556, 2025).
gram-negative bacterial infections (1 paper, 2022). Infections caused by bacteria that show up as pink (negative) when treated by the gram-staining method. "ClpP is considered a novel therapeutic target to combat different Gram-positive and Gram-negative bacterial infections." (PMID 36463962, 2022).
Leukoencephalopathy (1 paper, 2016). This term describes abnormality of the white matter of the cerebrum resulting from damage to the myelin sheaths of nerve cells. "We used the brain-MRI of patient 1.1 as a template to screen an Amsterdam brain-MRI database containing over 3000 unclassified leukoencephalopathy for comparable characteristics and selected three patients based on similarities in brain-MRI and clinical manifestations for targeted CLPP sequencing." (PMID 27899912, 2016).
malaria (1 paper, 2020). Malaria is a serious and sometimes fatal disease caused by a parasite that commonly infects a certain type of mosquito which feeds on humans. "Specific ClpP activators might thus be developed against a spectrum of pathogens including those not yet targeted by this approach, such as the malaria parasite Plasmodium falciparum." (PMID 32094149, 2020).
MELAS (1 paper, 2017). "The levels of LONP1 were increased in all mutant cybrid lines with exception of m.Trp cells, expression of AFG3L2 was induced in all disease cell models except MELAS, and the levels of CLPP were increased in MELAS, m.Val and m.ND6 cells, whereas they were reduced in MERRF and m.Trp cells." (PMID 28740091, 2017).
metastatic disease (1 paper, 2025). "In contrast, in advanced HCC and metastatic disease, ClpP is frequently overexpressed and represents a therapeutic vulnerability that can be targeted by small-molecule activators such as ONC206 and ONC212." (PMID 41155556, 2025).
Mitochondrial encephalopathy (1 paper, 2025). "In Dars2-deficient mouse models of mitochondrial encephalopathy, ClpP ablation preserved neuronal integrity, improved OXPHOS, and stabilized respiratory complex I and its supercomplexes." (PMID 41155556, 2025).
otitis externa (1 paper, 2025). Inflammation of the anatomical structures of the outer ear and ear canal secondary to an infectious process. "Moreover, consistent with our findings, Izabel’s study reported that all S. pseudintermedius isolates from dogs with pyoderma, otitis externa, and urinary tract infections also harbored hlb, while clpC and clpP have been implicated in cell formation and maintenance in S. aureus." (PMID 40333053, 2025).
squamous cell carcinoma (1 paper, 2021). A carcinoma arising from squamous epithelial cells. "The variant alleles G of SNP rs10420388 and A of SNP rs10418574 in the CLPP gene were associated with increased risk of squamous cell carcinoma (OR = 1.07 and 1.07; P = 0.013 and 0.016, respectively)." (PMID 34604049, 2021). "Notably, patients with rs10420388 and rs10418574 in CLPP showed a significantly increased risk of squamous cell carcinoma, while rs11126435 in M1AP was associated with decreased risk of adenocarcinoma." (PMID 34604049, 2021).
type 2 diabetes (1 paper, 2023). "Increased expression of HSP60, HSP10, LONP1 and ClpP protein was observed in the liver in an HFD-induced type 2 diabetes mouse model." (PMID 37095454, 2023).
uveal cancer (1 paper, 2021). A primary or metastatic malignant neoplasm that affects the choroid, ciliary body, or iris. "In several types of cancer (including breast, lung, and uveal cancer), overexpressed CLpP is associated with shorter metastasis-free survival." (PMID 34604049, 2021).
virus infection (1 paper, 2022). "Serendipitously during these experiments, the immunoblots of total H3 revealed the appearance of a smaller isoform in CLPP-null samples, of a size known for H3 proteolytic cleavage as cellular stress response, e.g., upon virus infection or DNA damage." (PMID 36611846, 2022).
cancer (63 papers, 2016 to 2025). A tumor composed of atypical neoplastic, often pleomorphic cells that invade other tissues. "Mitochondrial proteases are connected with cancer metabolic remodeling, and the loss of Lonp1 or ClpP resulted in attenuation of tumor proliferation and metastasis." (PMID 40943612, 2025). "ClpP is overexpressed in many human cancers and associated with poor prognosis in breast and lung cancer." (PMID 39261452, 2024). "Knockdown of ClpP is associated with reduced proliferation, migration, and invasion of various cancer cells." (PMID 35864539, 2022). "For ClpP, acyldepsipeptides (ADEPs), activators of compartmentalized proteases (ACPs), and imipridones act as agonists that can dysregulate ClpP, causing death in pathogenic bacteria and in cancer cells." (PMID 35245501, 2022). "The previously established association of the CLPP gene with cancer progression lends relevance to our findings." (PMID 34604049, 2021). "In contrast to the cytotoxic effects of inhibiting ClpP in cancer, normal cells are relatively insensitive to loss or inhibition of ClpP." (PMID 33037181, 2020). "Since the effect of ClpP on cancer cells is closely associated with its expression level, whether increasing or inhibiting ClpP activity is more effective in treating cancer needs to be further explored." (PMID 39261452, 2024). "ClpP is a highly conserved serine protease that is a critical enzyme in maintaining protein homeostasis and is an important drug target in pathogenic bacteria and various cancers." (PMID 35245501, 2022). "Overall, these findings indicate that ClpP overexpression seems to be a common feature of different cancers and, in some solid tumors, may be associated with a more aggressive disease, namely presence of metastases and poor RFS." (PMID 34207660, 2021). "While these studies provide valuable insights, our review aims to offer a comprehensive overview of ClpP agonists, focusing on their structural insights, physiological functions, and therapeutic potentials across multiple cancer types." (PMID 40395852, 2025). "Given these multifaceted physiological roles, ClpP has emerged as a potential therapeutic target, particularly in cancer, where its dysregulation can induce mitochondrial dysfunction and cell death." (PMID 41357605, 2025). "ClpP agonists represent a novel class of anti-cancer agents with promising results in many cancers, exemplified by the FDA-approved ONC201." (PMID 41333384, 2025). "While many of the direct results of ClpP activation have been identified, the mechanisms that inhibit cancer cell proliferation are only partially understood." (PMID 41333384, 2025). "Together, these findings position ZK53 as a promising therapeutic agent that sensitizes cancer cells to ferroptosis through ClpP activation and mitochondrial dysfunction." (PMID 41357605, 2025). "Compared to other cancer models where ClpP agonists induce apoptosis or other forms of cell death (i.e., ferroptosis), senescence predominates in the TNBC models tested here." (PMID 41333384, 2025). "Overactivation sustains tumor metabolism and survival; ClpP inhibition reduces cancer cell viability." (PMID 40943612, 2025). "This and other related small molecules referred to as ClpP agonists, exert antiproliferative effects in several cancer cell types." (PMID 41333384, 2025). "Recent investigations have revealed that ONC201, along with its imipridone analogs ONC206 and ONC212, bind to mitochondrial ClpP as an agonist, inhibiting oxidative phosphorylation as a component of its anti-cancer mechanism, eventually leading to apoptosis." (PMID 40145650, 2025). "As ONC201 induces ClpP activity, ClpP induces the integrated stress response pathway, which leads to disruption of mitochondrial function and inhibition of cancer cell survival." (PMID 41020897, 2025). "Recently, evidence suggests ClpP is overexpressed in many cancer cells and, as such, is an appealing target for drug therapy." (PMID 40395852, 2025).